CRP (C-reactive protein)
Diseases named in the same sentence as CRP in open-access papers (continued):
Sharing a sentence is not in itself a finding about the gene and the disease.
cryptococcosis (7 papers, 2017 to 2026). An acute or chronic, localized or disseminated infection by Cryptococcus neoformans. "In our study, erythrocyte sedimentation rate and C-reactive protein were increased in 5 cases (17.24%) and 3 cases (25%), respectively, which may be caused by cryptococcal infection." (PMID 35924106, 2022). "In this study, increased WBC (especially more than 20 × 109/L), and high levels of CRP and ESR were common in patients with disseminated cryptococcosis." (PMID 28532447, 2017). "Patients with disseminated cryptococcosis had higher WBC counts and elevated CRP levels than those without, but the difference was nonsignificant." (PMID 31828122, 2019).
deficiencies (7 papers, 2016 to 2025). "Some inflammatory biomarkers (e.g., CRP, orosomucoid and α-1 antitrypsin) were higher in CD than UC patients, and micronutrient deficiencies were more frequent in CD than UC patients, in agreement with previous findings." (PMID 27916926, 2016). "In a multiple logistic regression model, increased CRP levels were significantly associated with deficiencies of vitamin B12 (OR = 5.84; 95% CI 1.25–27.2; p = 0.024), folate (OR = 4.02; 1.87–8.66; p < 0.001), and with the presence of ≥ 2 micronutrient deficiencies (OR = 2.31; 1.21–4.42; p = 0.01)." (PMID 33026590, 2021).
diabetic ketoacidosis (7 papers, 2023 to 2025). The metabolic condition resulted from uncontrolled diabetes mellitus, in which the shift of acid-base status of the body toward the acid side because of loss of base or retention of acids other than carbonic acid is accompanied by the accumulation of ketone bodies in body tissues and fluids. "The symptoms and biomarkers of diabetic ketoacidosis are similar to that of infection, like fever, C reactive protein, and white blood cell count, since both create an environment of systemic inflammation." (PMID 37510185, 2023).
Down syndrome (7 papers, 2005 to 2025). "From the GxEmodel, variation at cg24317086 has been previously associated with gestational age, age in childhood, tissue type, Down syndrome, and C-reactive protein levels." (PMID 41136745, 2025). "Average levels of CRP for people with intellectual disability (male), cerebral palsy (male and female), Down syndrome (male and female), and severe motor and intellectual disabilities (male and female) were higher than the normal range (0–0.30 units)." (PMID 16584554, 2006). "Down syndrome patients had high levels of triglycerides and low levels of HDL, and high levels of CRP." (PMID 15705198, 2005). "The authors were able to show that CRP was a strong predictor of mortality independent of age, the presence of Down syndrome, or the use of advanced PAH therapies." (PMID 37176542, 2023). "Additionally, the Down syndrome cohort demonstrated a proinflammatory state not present in matched controls, with higher mean body mass index (BMI) (26.0 vs. 23.5 kg/m2, p < 0.001) and C-reactive protein (CRP) levels (29.3 vs. 14.5 mg/L, p < 0.001)." (PMID 37628350, 2023).
gallbladder cancer (7 papers, 2007 to 2026). "Recent publications have shown increasing levels of CRP are associated with increased risk of gallbladder cancer and other bile duct cancers." (PMID 28288186, 2017).
gram-negative bacterial infections (7 papers, 2018 to 2026). Infections caused by bacteria that show up as pink (negative) when treated by the gram-staining method. "At T24, the median CRP values were 38 mg/L for gram-positive bacterial infections other than CoNS, 40 mg/L for CoNS infections and 90 mg/L for gram-negative bacterial infections." (PMID 29382319, 2018). "The receiver operating characteristic (ROC) curve was constructed to compare the diagnostic accuracy of HBP, procalcitonin (PCT), and C-reactive protein (CRP), as well as their value in differentiating Gram-positive bacteria and Gram-negative bacterial infections." (PMID 39611102, 2024).
granulomatosis with polyangiitis (7 papers, 2018 to 2025). A small-vessel necrotizing vasculitis characterized by the association of inflammation of the vessel wall and peri- and extravascular granulomatosis. "Also, the diagnosis of microscopic polyangiitis (MPA), compared to granulomatosis with polyangiitis (GPA), yielded higher sTCC levels, and plasma C-reactive protein levels correlated significantly to sTCC." (PMID 40440129, 2025).
gynecological cancer (7 papers, 2017 to 2024). "Combined hazard ratios (HRs) and 95% confidence intervals (CIs) were used to estimate the prognostic effect of the CRP/Alb ratio in gynecological cancers." (PMID 34778051, 2021). "Recently, CRP has proved a predictive factor in certain human cancers such as gastrointestinal, breast, lung, and gynecologic cancers." (PMID 28209200, 2017). "Advanced age, high BMI, high preoperative CRP levels, distant organ metastasis, extensive surgery, long operation times, and high intraoperative blood transfusion were found to be independent risk factors for postoperative AKI in patients undergoing gynecological cancer surgery." (PMID 37575800, 2023). "The sex-related difference in CRP distribution showed that CRP levels were higher in males with different TNM stages, BMI, and tumor types (except for female reproductive cancer) than in females." (PMID 35752767, 2022).
helminth infection (7 papers, 2014 to 2024). "Additionally, the subgroup analyses were performed by indicator (season, AGP, CRP and helminth infections)." (PMID 37974246, 2023). "This study also found that 8.3% of women had elevated CRP levels that could not be explained by underlying bacterial infection (see exclusion criteria), helminthic infection or other variables." (PMID 38937587, 2024). "For example, IL-4 could signal through IL-4Rα to trigger specialized macrophage activation, promoting the mitigation of helminthic infection and tissue repair in the liver and lung, or reduce the production of C-reactive protein (CRP) by human primary hepatocytes." (PMID 34307393, 2021). "Additionally, CRP was the only marker used to measure inflammation during pregnancy; previous studies have indicated eosinophils, IgE, and other cytokines could be more specific inflammatory markers of helminth infection." (PMID 33739991, 2021). "Interestingly, ongoing helminth infection did not further influence the serum levels of cytokines and CRP of TB patients from TZ (P>0.05)." (PMID 28759590, 2017). "VAD prevalence was higher during the dry vs. rainy season, in the presence of CRP ≥ 5.0 mg/L, in AGP < 1.0 g/L, and in the absence of helminth infections." (PMID 37974246, 2023).
Hypocholesterolemia (7 papers, 2012 to 2025). An decreased concentration of cholesterol in the blood. "Additionally, they observed a close correlation between elevated CRP levels, reduced serum albumin levels, and hypocholesterolemia." (PMID 40339352, 2025).
IgA nephropathy (7 papers, 2015 to 2025). "For example, Immunosuppressant agent such as corticosteroids can raise the WBC or neutrophil count and MMF is associated with lower CRP concentration in kidney, cardiac transplant recipients and patients with IgA nephropathy." (PMID 26275220, 2015). "Similarly, a small study on IgA nephropathy found that higher CRP levels predicted kidney function decline." (PMID 40623816, 2025). "Clinically, at least in our medical center, CRP and IL-6 are not routine examination items for patients with IgA nephropathy, and there is no guideline recommending routine examination of CRP and IL-6 in IgAN patients." (PMID 35664006, 2022).
ischemic cardiomyopathy (7 papers, 2016 to 2025). Ischemic cardiomyopathy is a cardiomyopathy in which a weakness in the muscle of the heart due to inadequate oxygen delivery to the myocardium with coronary artery disease being the most common cause. "In patients with ischemic cardiomyopathy, polymorphism in CCL2 gene (CCL2-2518 A/G single nucleotide polymorphism) was correlated with C-reactive protein (CRP) level." (PMID 27242392, 2016). "Another study by the same group, involving 38 patients with ischemic cardiomyopathy, showed that PTX significantly improved LVEF and reduced inflammatory markers such as TNF-α and C-reactive protein (CRP)." (PMID 41066529, 2025).
limb ischemia (7 papers, 2018 to 2025). A ischemia that involves the limb. "In previous studies, C-reactive protein (CRP), platelet aggregation, and NLR were defined as effective predictive values for limb ischemia." (PMID 34659947, 2021).
lipid metabolism disorders (7 papers, 2020 to 2024). "CRP can not only aggravates the inflammatory reaction, but also reduces the sensitivity of tissue cells to insulin, and play a certain role in lipid metabolism disorder." (PMID 35784937, 2022). "In this study, we confirmed the association of Moyamoya disease progression with inflammatory changes and lipid metabolism disorders by observing hemodynamic changes through SPECT, as well as increased CRP and triglyceride levels." (PMID 38167529, 2024).
manic episodes (7 papers, 2015 to 2025). "A study encompassing 8,332 BD patients revealed that elevated levels of CRP during manic episodes persisted even after adjustments for confounding variables, including age, sex, BMI, psychotic symptoms, and age at onset." (PMID 40256164, 2025). "We were able to replicate previous findings of increased CRP levels in BD patients suffering from a manic episode as compared to euthymic and depressed patients." (PMID 31788733, 2019). "Further analyses showed that depressed men with high levels of diurnal cortisol slope and CRP had an increased odds (OR=10.99, p=.001) of having a (hypo)manic episode." (PMID 26196286, 2015). "Another explanation might be that increased CRP is due to activation of the stress axis in manic episodes because of the general increase in activity (psychomotor activity, lack of sleep, etc.)." (PMID 31788733, 2019). "That is, depressed men with high levels of diurnal cortisol slope as well as CRP had an increased odds of having a lifetime (hypo)manic episode, which may have resulted from a higher allostatic load." (PMID 26196286, 2015). "However, we suggest that CRP is closely related to manic episodes, especially in male patients." (PMID 30762747, 2019). "Therefore it is difficult to define a cut-off CRP level that could be used as an early detection for emerging manic episodes in the individual patient as well as use this as a prognostic marker for a more severe course or development of comorbid somatic diseases." (PMID 31788733, 2019). "In patients experiencing a manic episode, pro‐inflammatory cytokines (e.g., TNF‐α, IL‐1, IL‐6), soluble receptors of IL‐2, soluble TNF‐α receptor type 1 (sIL‐2R and sTNFR1, respectively), and C reactive protein (CRP) are generally increased when compared to a control population." (PMID 34590391, 2022).
mesothelioma (7 papers, 1998 to 2025). A usually malignant and aggressive neoplasm of the mesothelium which is often associated with exposure to asbestos. "In mesothelioma patients, high CRP and low albumin levels have been strongly associated with poor prognosis." (PMID 40282547, 2025). "A fair prognostic ability of NLR, PLR, CRP, and fibrinogen with respect to overall survival has been demonstrated in the literature in mesothelioma as well as in other malignancies." (PMID 40282547, 2025). "However, inflammatory biomarkers (CRP, cytokines, and white cell counts) can be independent prognostic factors in a variety of tumours (oesophageal, gastric, pancreatic, colorectal, mesothelioma, ovarian, renal, and bladder)." (PMID 28572821, 2017). "However, in contrast to those studies mainly on mesothelioma, CRP was the only investigated inflammatory parameter that did not prove prognostic significance in SFT based on univariate survival analyses and thus was not further included in the multivariate testing." (PMID 28970578, 2017). "In the present study, we investigated the prognostic and predictive power of a novel inflammation-based system—the Mesothelioma Systemic Inflammation Score, a product of NLR, PLR, CRP, and fibrinogen—in a large cohort of pleural mesothelioma patients treated in a high-volume center." (PMID 40282547, 2025).
metastatic prostate carcinoma (7 papers, 2009 to 2023). A carcinoma that arises from the prostate gland and has spread to other anatomic sites. "In evaluating a cohort of 62 patients with metastatic prostate cancer on androgen deprivation therapy, CRP and PSA were evaluated simultaneously; higher levels of both CRP and PSA were independent predictors of poorer cancer-specific survival." (PMID 34512646, 2021). "In particular, the systemic inflammatory response, as evidenced by an elevated C-reactive protein (CRP), has been shown to be independently associated with poor prognosis in localised and metastatic prostate cancer." (PMID 23768149, 2013).
mucormycosis (7 papers, 2021 to 2025). "Deep-seated fungi diseases like Mucormycosis are linked to high levels of CRP in terms of their capacity to cause high (> 100 mg/L) values." (PMID 38800245, 2024). "CRP is an important biomarker in assessing the septic response to COVID-associated rhino-orbito-cerebral mucormycosis." (PMID 38800245, 2024). "The median CRP level on Day 5 was 10.3 in the non-Mucormycosis group with an Interquartile range of 3.3-20.5 (p =0.005)." (PMID 38800245, 2024). "As is evident from the figure, The marginal means of CRP values among patients with Mucormycosis was higher compared to patients with non-Mucormycosis across various follow-up periods." (PMID 38800245, 2024). "The median CRP level on Day 15 was 21.8 in the Mucormycosis group with an Interquartile range of 38.6-82.5." (PMID 38800245, 2024). "There was a significant difference between Mucormycosis and Non-Mucormycosis groups in CRP-level kinetics." (PMID 38800245, 2024). "In our study also, a similar finding was observed on day 1 of admission the mean serum CRP level was 36.4 mg/L in the Mucormycosis group and 6.4 mg/L in the non-Mucormycosis group." (PMID 38800245, 2024). "The median CRP level on Day 15 was 9.4 in the non-Mucormycosis group with an interquartile range of 7.4-11.5 (p =0.002)." (PMID 38800245, 2024). "The median CRP level on Day 1 was 14.4 in the Mucormycosis group with an Interquartile range of 33.1-61.3." (PMID 38800245, 2024). "The median CRP values among patients with Mucormycosis was significantly higher compared to patients with non-Mucormycosis across various follow-up period time." (PMID 38800245, 2024). "The mean CRP level on Day 5 was 51.8 (SD=37) in the Mucormycosis group and 20 (SD=23.3) in the non-Mucormycosis group." (PMID 38800245, 2024). "Cases with invasive mucormycosis had a higher level of inflammatory markers (hs-CRP and ESR, P=<0.001 and 0.002, respectively), compared to the controls." (PMID 35528622, 2021). "The serum CRP levels decreased in non-Mucormycosis cases after the fifth postoperative day." (PMID 38800245, 2024). "This post-surgical rise in levels of CRP explains the rise in levels of CRP in our patients of the Mucormycosis group who underwent surgical debridement of the nose and paranasal sinuses for mucormycosis." (PMID 38800245, 2024). "Whether high CRP levels contributed to the development of mucormycosis or mucormycosis led to high serum CRP is a matter of research." (PMID 38800245, 2024). "Even though CRP is a non-specific inflammatory marker, deep-seated fungal illness, such as mucormycosis, is associated with elevated levels of CRP 100-300 mg/L, especially in immunocompromised people." (PMID 38800245, 2024). "In the Mucormycosis group, the CRP levels flattened or decreased slowly with time." (PMID 38800245, 2024). "Hence, we recommend CRP monitoring of in-patients of mucormycosis on a global standard after further studies on a larger scale." (PMID 38800245, 2024). "The serum CRP levels in all of our Mucormycosis cases were high with a mean value of 36.4 mg/L." (PMID 38800245, 2024). "Hence, we recommend monitoring serum CRP among in-patients of mucormycosis on a global standard after further studies on a larger scale." (PMID 38800245, 2024). "Between the 5th and 15th day of the in-patient stay, the CRP level flattened or decreased slowly with time and all the patients in the Mucormycosis group recovered completely without any fatality." (PMID 38800245, 2024). "The mean CRP level on Day 15 was 52.3 (SD=36.5) in the Mucormycosis group and 12 (SD=12.1) in the non-Mucormycosis group." (PMID 38800245, 2024). "The mean CRP level on Day 1 was 36.4 (SD=29.8) in the Mucormycosis group and 6.4 (SD=5.3) in the non-Mucormycosis group." (PMID 38800245, 2024).
nicotine dependence (7 papers, 2014 to 2025). Physical and psychological dependence on nicotine. "Second, regarding risky behaviors, nicotine dependence was associated with significantly higher levels of CRP and IL-6, and risky alcohol use was marginally associated with lower IL-1ra (p = 0.08)." (PMID 41267823, 2025). "In our high-risk sample, we found that nicotine dependence was associated with higher levels of pro-inflammatory markers CRP and IL-6, while alcohol use was associated with lower levels of anti-inflammatory marker IL-1ra." (PMID 41267823, 2025). "Increased CRP has also been associated with high nicotine dependence in SZ smokers and one study has suggested that increased CRP was associated with sedentary behavior." (PMID 30190688, 2018). "CRP levels ≥ 3 mg/L were associated with severe nicotine dependence (29 vs. 15%, OR = 2.8, p = 0.003) and BMI (OR = 1.1, p < 0.0001), independently of socio-demographic characteristics and antidepressant intake." (PMID 30190688, 2018). "Additionally, higher ELS was associated with higher IL-1ra (r = 0.19), nicotine dependence was positively associated with higher CRP (r = 0.30) and IL-6 (r = 0.36), and physical activity (r = −0.18) and nutrition (r = −0.20) were negatively correlated with IL-6 (all rs p < 0.05)." (PMID 41267823, 2025). "Reported outcomes include pulmonary function (e.g., FEV1), inflammatory and oxidative stress biomarkers (e.g., TNF-α, IL-6, CRP, 8-OHdG), nicotine dependence scores, salivary cotinine levels, oral health indices, and other exposure-related markers." (PMID 41281023, 2025). "Abnormal CRP levels have been further associated with increased nicotine dependence in two studies, but not with daily tobacco smoking." (PMID 30190688, 2018).
oral cavity cancer (7 papers, 2013 to 2025). A primary or metastatic malignant neoplasm involving the oral cavity. "Special attention should be given to women, patients with oral cavity cancer, worse performance, previous mental health problems, daily smokers, and those with higher CRP and flatter cortisol slope." (PMID 40877705, 2025). "Some inflammatory markers such as interleukin-6, tumor necrotic factor, and C-reactive protein (CRP) were recently identified as prognostic markers in oral cavity cancer." (PMID 28209200, 2017). "Our previous studies showed a positive relationship between CRP level elevation and advanced oral cavity cancer stage." (PMID 28209200, 2017). "In this study, we recruited more cases (343 cases) to evaluate the connection between preoperative serum CRP level, oral cavity cancer stage, and prognosis." (PMID 28209200, 2017). "The mean CRP level was 5.90 mg/L (±SD 10.53), 8.37 mg/L (±SD 15.01), and 6.52 mg/L (±SD 8.90) in tongue cancer, buccal cancer, and other oral cavity cancers, respectively." (PMID 28209200, 2017). "Patients with recurrent oral cavity cancer typically present superimposed lung infection, which further elevates the serum CRP level." (PMID 25061977, 2014). "However, the level of CRP increased, similar to Moon‘s study, which prospectively analyzed 153 patients with non-oral cavity cancer receiving CCRT." (PMID 34359287, 2021). "Therefore, CRP has the potential to be a biomarker for oral cavity cancer and a predictor of prognosis before treatment." (PMID 28209200, 2017).